TNF (tumor necrosis factor)
Diseases named in the same sentence as TNF in open-access papers (continued):
Sharing a sentence is not in itself a finding about the gene and the disease.
diabetes (continued). "Elevated IL6 and TNF levels have been observed in patients with type 2 diabetes, and these cytokines are linked to disease progression through pathways such as AGE-RAGE signaling pathways associated with diabetes complications." (PMID 40699728, 2025). "Furthermore, joint pathway analysis further confirmed that the AGE-RAGE signalling pathway, the TNF signalling pathway, and the IL-17 signalling pathway are also key mechanisms mediating the hypoglycaemic efficacy of AR in diabetes and its complications." (PMID 41141342, 2025). "Elevated IL-6, CRP, and TNF-α levels have been reported in AD patients with diabetes mellitus." (PMID 41294487, 2025). "The consistent association observed in our study invites the hypothesis that resistin and TNF-α may be interact within the shared inflammatory pathway of periodontitis and diabetes." (PMID 41244040, 2025). "By suppressing TNF-α in host cells, 4HR could mitigate chronic inflammation that exacerbates muscle wasting in diabetes." (PMID 39832033, 2025). "In those diabetes participants where S‐specific T cells were detected, the response was unfocused, with the expected expression of IFNγ, TNF, and IL‐2, alongside a significant increase in the expression of the Th2 cytokine IL‐13 in S‐specific CD4+ and CD8+ T cells from both diabetes groups." (PMID 41367201, 2025). "TNF pathway plays a crucial role in linking chronic inflammation, metabolic dysfunction, and cancer progression, providing an everyday mechanistic basis for its involvement in diabetes and BC." (PMID 40547917, 2025). "Tumor necrosis factor-α plays a central role in the inflammatory pathway linking OSA to diabetes." (PMID 41155523, 2025). "Macrophages, which play a crucial role in initiating immune responses by phagocytosing TB bacteria and secreting key cytokines such as TNF-α and IL-6, demonstrate impaired functionality in individuals with diabetes due to the presence of chronic, low-grade inflammation." (PMID 40917351, 2025). "Research involving obese murine models has demonstrated that the administration of oxidase inhibitors leads to increased adiponectin expression and decreased TNF-α expression, thereby mitigating complications such as diabetes, hyperlipidemia, and hepatic steatosis." (PMID 39606575, 2024). "Therefore, we conducted novel research to determine the levels of serum adiponectin, hs-CRP, and TNF-α in elderly patients with diabetes, MCI, and symptoms of depression." (PMID 39409133, 2024). "Since 2019, thirteen keywords, including “mortality,” “mitochondrial biogenesis,” “diabetes mellitus,” “vitamin D,” “cells,” “TNF-α,” “muscle mass,” “mechanisms,” “injury,” “insulin resistance,” “resistance,” “autophagy,” and “protein,” have begun to emerge prominently." (PMID 39588187, 2024). "Furthermore, TNF-α has been compromised in the formation of type 2 diabetes mellitus, chronic inflammation, cardiometabolic illnesses, and various malignancies." (PMID 39149648, 2024). "TNF-α has a significant role in the development of diabetes, particularly T2DM." (PMID 39328924, 2024). "To further examine whether neutrophils are also primed for inflammatory cytokine production during diabetes, we measured the protein levels of tumor necrosis factor-α, interleukin-8 (IL-8), and IL-1β in neutrophils." (PMID 38654733, 2024). "Our study showed that diabetes suppressed TNF-α responses, which may impair viral clearance and worsen disease outcomes by perpetuating immune dysfunction." (PMID 39456722, 2024). "In the context of diabetes, elevated Ac-H3 levels are generally observed in STZ-induced diabetic animals, often linked to increased expression of pro-inflammatory cytokines such as tumor necrosis factor-α (TNF-α) and cyclooxygenase-2 (COX-2)." (PMID 39596347, 2024). "Since TNF-α, NF-κB, and AGEs are key contributors to the development and progression of diabetes, γ-lactams could be promising bioactive molecules for diabetes management." (PMID 38731463, 2024).
diabetes (continued). "Moreover, Amini and colleagues, demonstrated how tropisetron’s down-regulation of TNF-α and IL-6 levels had an anti-inflammatory effect on diabetes-induced liver abnormalities." (PMID 38629089, 2024). "In diabetes, persistent hyperglycemia leads to “a state of chronic low-grade inflammation, characterized by elevated levels of pro-inflammatory cytokines such as tumor necrosis factor-alpha (TNF-α), interleukin-1 beta (IL-1β), and IL-6." (PMID 39139325, 2024). "That is why MDA and TNF-α levels in the specific condition of diabetes will be higher." (PMID 38266537, 2024). "The present findings showed that voluntary exercise could have therapeutic effects on diabetes mellitus type 2, and it improved its pulmonary complication by elevation of the levels of Nrf2, IL-10, and IL-11 as well as decreasing TNF-α and NF-kB levels." (PMID 38164478, 2024). "Clinical studies have found that TNF-α is significantly increased in patients with diabetes." (PMID 39144694, 2024). "However, during pre-diabetes, oxidative stress has been shown to activate pathways that release pro-inflammatory cytokines such as TNF-α, IL-6 and CRP." (PMID 39596174, 2024). "Additionally, both diabetes mellitus and programmed cell death protein 1 (PD-1) expression on CD3+/CD4+ T cells negatively impacted TNF-α levels, while body mass index was inversely associated with IFN-γ production." (PMID 39456722, 2024). "Probiotic supplementation via activating AMPK/SIRT1/PI3K/mTORc2/AKT/Nrf2 pathways resulting in blocking TNF- α or decreasing its level, could prevent the progression of diabetes or NAFLD." (PMID 38504163, 2024). "In diabetes induced animal model, the leaf extract reduced the circulatory levels of inflammatory markers such as Interleukin-1 beta (IL-1β), Interleukin 6 (IL-6), and TNF-α." (PMID 39479139, 2024). "In addition, we did not observe any elevation in cytokines associated with both an immune response and the development of diabetes (IL-1β, IL-6, IL-8, and TNFα) using ddPCR." (PMID 38400070, 2024). "Tumor necrosis factor (TNF)-α, an inflammatory cytokine, plays a pivotal role in the disruption of vascular circulation, causing endothelial dysfunction in many pathophysiological conditions including diabetes and metabolic syndrome." (PMID 39635433, 2024). "Increased levels of CRP, IL-6, and TNF-α were also revealed in patients with both diabetes and MCI." (PMID 38396924, 2024). "Diabetes is an inflammatory disease, and elevated blood glucose level and insulin insensitivity leads to the activation of immune cells, thereby secreting interleukins and cytokines such as IL-6 and TNF-α and aggravating the inflammatory response." (PMID 39144694, 2024). "Plasma mtDNA was positive correlation with TNFα in diabetes patients by multiple linear regression." (PMID 38241222, 2024). "Univariate logistic regression analysis identified significant independent predictors of ACS, including age, gender, history of diabetes, smoking history, TGs, TNF-α, IL-6, ceramide (d18:1/16:0), ceramide (d18:1/18:0), ceramide (d18:1/24:0), ceramide (d18:1/20:0) and ceramide (d18:1/22:0)." (PMID 38218768, 2024). "Furthermore, diabetes is known to induce pro-inflammatory markers, such as cytokines, including several interleukins and tumor necrosis factor, by the activation of various biochemical parameters, such as C-reactive protein." (PMID 39257852, 2024). "Therefore, uncontrolled diabetes, characterized by chronic low-grade inflammation, leads to increased production of TNF-α, which worsens periodontal inflammation." (PMID 39409052, 2024). "Also, TNF-α linkage with various diseases such as diabetes has served to excite its link to oral carcinogenesis." (PMID 38406163, 2024). "The multifactorial effects of liraglutide also encompassed a reduction in TNFα level, which might be considered an important factor in the protective effects of the drug in the course of organ damage in diabetes mellitus." (PMID 39452935, 2024).
diabetes (continued). "Thus, there is a need for more prospective cohort studies to get a more accurate relation between serum TNF-α levels and the risk of DPN in diabetes patients." (PMID 38179375, 2023). "Diabetes promotes the production of IL-1β and TNF-α by macrophages, which may contribute to the enhancement of peri-implant infection." (PMID 36875028, 2023). "Hypertension and diabetes were more common in male subjects compared to female subjects (p < 0.05).Increased physical activity both at baseline and follow up were associated with decreased BMI, WC and inflammatory markers, including us-CRP and TNF." (PMID 37107201, 2023). "This observed trend was also noticed in other animal models of high-fat diet or streptozotocin-induced diabetes, where probiotic Lactobacillus plantarum increased the expression of IL-10 while decreasing the expression of TNF-α and IL-6, providing immunomodulatory characteristics of probiotics." (PMID 37894792, 2023). "In addition, higher levels of TNF-α, CC chemokine receptor 5 (CCR5) and CXC chemokine receptor 3 (CXCR3) at peri-implant sites in patients with chronic periodontitis and diabetes suggest a high potential for peri-implant bone loss." (PMID 36875028, 2023). "Reduced expression of diabetes-related markers.Increased abundance of Firmicutes.Increased Firmicutes to Bacteroidetes ratio.Decreased abundance of Bacteroidetes and Eubacterium.Downregulated serum LPS and TNF-α." (PMID 37795371, 2023). "Furthermore, damage to the liver and kidneys and the increased secretion of TNF-α from adipocytes aggravate not only dry skin but also diabetes." (PMID 37374121, 2023). "In addition, blocking TNF-a using a murine anti-TNF-a antibody confers kidney protection compared to that in a vehicle-treated Ins2Akita (with diabetes) mice." (PMID 37859695, 2023). "Similarly, weekly intraperitoneal injections of 50 μg/mL of anti-IL-17A significantly decreased (p < 0.05) diabetes-mediated IL-1β, IL-6, TNF-α, and ZO-1 degradation in the retinas of db/db-Type II diabetic mice 2 months post-diabetes." (PMID 36674854, 2023). "We next analyzed whether sex, presence or absence of bio-switch, arthritis, scalp, nail or genital lesions, diabetes, current smoking status or history of tuberculosis affected the treatment response to TNF-α inhibitors." (PMID 36769622, 2023). "The diabetes-related soluble factors, such as TNF-α, may play an important role in regulating Tim-3 expression." (PMID 37082729, 2023). "Additionally, TNF-α is found to take a significant part in the process of medial calcification in people with diabetes and CKD." (PMID 37964312, 2023). "The main contribution of this research was that diabetes enhances the lung injury and inflammation in rats due to elevated levels of TNF-α, IL-6, and IL-1β and lower levels of IL-10, lower SOD and GPx activity, TAC levels, and increased MDA and NO levels in tissue and BALF." (PMID 37520024, 2023). "Furthermore, several studies have found elevated levels of IL6 and TNF-α in patients with insulin resistance and clinically diagnosed diabetes." (PMID 35237941, 2023). "Metabolic inflammation mediated by various pro-inflammatory cytokines (e.g., tumor necrosis factor-α-TNF-α) and chemokines (e.g., chemokine C-C motif ligand-2 and-5) has been recognized to be the leading cause of the onset and advancement of diabetic complications." (PMID 37032781, 2023). "TNF-α plays a key role in the development of diabetes in atherosclerosis." (PMID 37240440, 2023). "Patients with diabetes mellitus were more likely to receive JAKis than non-TNF inhibitors." (PMID 36626396, 2023). "While IL-1β, IFNγ and TNFα have all been detected in islet infiltrates from human donors with type 1 diabetes, most of our understanding of their effects and functional pathobiology in diabetes comes from rodent model systems." (PMID 37113489, 2023). "Diabetes is associated with changes in GSH metabolism, which may possibly contribute to an increase in TNF-α and IL-1b." (PMID 37371821, 2023).
diabetes (continued). "TNF-α, previously identified for its immunological and inflammatory effects, is now being recognized to play a major role in the complicated pathways contributing to neuropathic problems in diabetes." (PMID 38179375, 2023). "In addition, the expression of TLR4 mRNA and the protein levels TNF-α were increased in the spinal cord of streptozotocin-induced diabetes." (PMID 36946851, 2023). "However, associations of IL-1β, IL-10, IL-12 p70, MCP-3, and TNF-α with TIR remained significant after adjustment to BMI, as well as other possible confounders (age, sex, diabetes duration, and eGFR)." (PMID 37893217, 2023). "Moreover, it inhibited diabetes-induced neuroinflammation by decreasing the inflammatory markers NfκB, TNF-α, IL-1β, and IL-6 and downregulating the BDNF/ERK/CREP pathway." (PMID 38105928, 2023). "We determined the level of tissue cytokines (TNF-α and IL-6) in the brain and liver, seeing as alloxan-induced diabetes is characterized by cytotoxicity in the pancreas, brain (neuronal degeneration and necrosis), kidney (nephrosis, nephritis), and liver (hepatitis)." (PMID 37629665, 2023). "Diabetes increases inflammation in periodontal tissues, with higher levels of inflammatory mediators such as interleukin-1β (IL-1β) and tumour necrosis factor-α (TNF-α)." (PMID 36981453, 2023). "Additionally, experimental studies have demonstrated that rodents with diabetes have reduced levels of microRNA-146a, and its dysregulation seems to occur with stimuli such as increased NF-κB, TNF-α, and IL-1β expression." (PMID 37585913, 2023). "In patients with diabetes and neuropathy, in addition to TNF-α, IL-6 production is increased." (PMID 37686346, 2023). "The activity of inflammatory cytokines such as interleukin-1 beta (IL-1β) and tumor necrotic factor-alpha (TNF-α) as well as the pro-inflammatory transcription factor, nuclear factor kappa B (NFκB), has been found to be significantly increased in diabetic retina." (PMID 37268913, 2023). "Consequently, this modulation influences the severity of various ailments such as Alzheimer’s disease, myocardial disorders, and diabetes by impacting the expression of pro-inflammatory cytokines like IL-1β, IL-6, TNF-α, and type 1 interferons." (PMID 38001481, 2023). "Therefore, this study confirmed that a mixture of Korean red ginseng and probiotics, which are known to be effective in treating diabetes and general wounds, can help heal wounds by controlling the expression of TNF-α, MMP-9, TIMP-1, and NF-κB." (PMID 37374359, 2023). "In addition, PAP1 prevented the diabetes-induced repolarization defects through reducing the secretion of the inflammatory cytokines IL-10, IL-12p70, GM-CSF, IFNγ, and TNFα." (PMID 34623540, 2023). "Experimental evidence found that patients with diabetes have chronic low-grade inflammation marked by higher levels of pro-inflammatory mediators including C-reactive protein, interleukin 6, and tumor necrosis factor alpha, as well as abnormal cytokine-secreting cells." (PMID 37478111, 2023). "Moreover, a study reported that hesperidin had significant role in the suppression of inflammatory markers such as tumor necrosis factor alpha (TNFα) and interleukin 6 (IL-6) in patients with type 2 diabetes mellitus." (PMID 37082190, 2023). "Similarly, in an 18-week randomized controlled study involving 33 type 2 diabetes mellitus patients, supplementation with 900 mg/day of Brazilian green propolis significantly reduced serum TNF-α levels but significantly increased serum IL-1β and IL-6 levels." (PMID 37111285, 2023). "Anti-TNFα therapy on those already diagnosed with diabetes has seen mixed results." (PMID 37483613, 2023). "Moreover, the regulation of inflammation through TNFα and NFκB prevented transgenic fat-1 mice from developing streptozocin-induced diabetes during which elevated levels of the RvE1 precursor 18-HEPE were detected." (PMID 37686333, 2023).
diabetes (continued). "However, co-existence of hypertension and diabetes mellitus increased TNF-α release compared to either group alone." (PMID 36056287, 2023). "TNF-α-mediated suppression of LPL has been clearly demonstrated in the adipose tissue, and is associated with clinically elevated TGs in patients with diabetes." (PMID 36208911, 2023). "Diabetes is associated with chronic inflammation, which is mainly due to increased plasma concentrations of C-reactive protein (CRP), fibrinogen, interleukin-6 (IL-6), interleukin-1 (IL-1), and TNF α." (PMID 37974282, 2023). "TNF, IL1, IL6, IL18, IL8, intracellular and vascular cell adhesion molecules, matrix metalloproteinases, and monocyte chemoattractant protein 1 (MCP-1) are all upregulated in diabetes and have been connected to its associated complications." (PMID 37047011, 2023). "Similarly, metformin significantly (p < 0.05) decreased the levels of hepatic TNF-α and IL-6 by about 84% and 87%, respectively, in rats with diabetes in comparison to only rats with diabetes." (PMID 37280499, 2023). "Moreover, the pro-inflammatory mediators IL-6, IL-1β, and TNF-α are elevated in diabetes-induced anxiety and depression." (PMID 38105928, 2023). "Furthermore, Baggiolini, Dewald observed enhanced TNF-α, IL-1β, and IL-8 levels in neutrophils in patients with diabetes." (PMID 37893490, 2023). "Furthermore, diabetes patients had three- to fourfold upregulate levels of circulating TNF-alpha than healthy controls." (PMID 36622512, 2023). "In patients with diabetes, the accumulation of AGEs in the liver and kidneys is increased, indicating the possibility that AGEs are involved in the increased production of TNF-α in these organs." (PMID 37374121, 2023). "It was found that the plasma and vitreous concentrations of TNF-α were increased in patients with diabetes, and the plasma TNF-α concentration was related to the severity of DR.In diabetic rats, the vitreous TNF-α concentration was related to the increased permeability of BRB." (PMID 37334304, 2023). "TNF-α may promote diabetes autoimmunity by enhancing the recruitment of inflammatory cells to the islets, activating cells, and enhancing autoantigen presentation." (PMID 38096190, 2023). "gingivalisLPS induction may produce apical periodontitis and evaluated the changes in IL-6 and TNF-a expression on macrophages after 14, 28, and 42 days in a diabetes mellitus rat model." (PMID 36599453, 2023). "Marine omega-3 fatty acid (fish oil) supplementation has also been shown to reduce CRP in randomized trials among maintenance hemodialysis patients and those with end-stage renal disease, and to reduce TNF-α and interleukin (IL)-6 among patients with diabetes and chronic heart failure." (PMID 36558465, 2022). "They demonstrated that median IL-6 and TNF-α were higher in diabetes compared to non-diabetes (p < 0.01), suggesting that diabetes was strongly associated with elevated levels of IL-6 and TNF-α." (PMID 36140983, 2022). "Here, diabetic mice showed activation of NF-κB and increased expression of IL-6 and TNF-α, we found kirenol could inhibit NF-κB activation as well as gene expression of IL-6 and TNF-α induced by diabetes." (PMID 36073930, 2022). "For example, mitochondrial dysfunctions have been unraveled in various autoimmune diseases, such as RA, SLE, and diabetes, while the expression of pro-inflammatory cytokines such as TNF-α, IL-6, and IL-1β is upregulated in the adipose tissues of obese and diabetic subjects." (PMID 35997820, 2022). "At the same time, the mRNA expression of IL-6, ICAM, and TNF-α in retinal tissue began to be highly expressed in the diabetes group on the 8th day after induction, and the difference was statistically significant compared with that in the normal group at the same time point (P < 0.01)." (PMID 35126785, 2022).